ALB (albumin)
Diseases named in the same sentence as ALB in open-access papers (continued):
Sharing a sentence is not in itself a finding about the gene and the disease.
kidney damage (continued). "Albumin, urea, and creatinine levels in the serum were assessed to monitor changes in kidney function, whereas renal KIM-1 was used as an indicator of kidney damage." (PMID 40006061, 2025). "Urine markers of kidney damage were improved, as evidenced by lower urinary levels of NGAL, clusterin, and albumin." (PMID 37047807, 2023). "A significant eight-fold increase in urinary albumin was observed in the CKD+HP group, as a possible expression of the greater kidney damage induced by the CKD plus the high P exposure." (PMID 36986200, 2023). "Of the four diets used in the present study, the ER and TR diets were more effective in reducing kidney damage during AKI, although the IF diet also reduced serum urea, creatinine, and urinary albumin excretion." (PMID 36941590, 2023). "Urinary albumin–creatinine ratio (UACR) was firstly divided into the ≥30-mg/g group, indicating kidney damage, and <30-mg/g group." (PMID 35669685, 2022). "Previous studies suggested that central and peripheral BP are correlated with urinary albumin excretion and ACR, suggesting that BP has a clear predictive effect on kidney damage." (PMID 35865385, 2022). "For the best exploration of kidney damage alleviated by emodin, Scr, BUN, and urine albumin/creatinine were measured." (PMID 34159197, 2021). "The decreased albumin uptake leads to elevated intratubular albumin concentration, stimulating NHE3 activity and further worsening kidney damage." (PMID 34884494, 2021). "Urine albumin–creatinine ratio (UACR) and urine protein–creatinine ratio (UPCR) are important markers of kidney damage." (PMID 33096837, 2020). "The urine albumin-to-creatinine ratio (UACR) is recognized as the earliest and most precise marker of kidney damage and cardiovascular mortality in CKD patients." (PMID 29311711, 2018). "Mice treated with STZ alone showed liver damage and kidney damage as evidenced by significant increase in the serum activities of AST and ALT, and levels of BUN, CRE and ALB when compared with NC groups (all with P < 0.01)." (PMID 26683206, 2015). "Among them, 19 people with kidney damage were identified (14.0 %; 95 % CI 8.1–19.9), of whom 11 had an RBP level above the threshold and 14 excessive albumin excretion." (PMID 25971522, 2015). "In comparison with cancer control rats, nephropathy markers like BUN and creatinine levels, show significant increase by cisplatin treatment and a decrease in albumin level." (PMID 19356226, 2009). "CKD was defined solely based on eGFR assessment, as markers of kidney damage like urinary albumin-to-creatinine ratio were not consistently available in this retrospective cohort." (PMID 41590250, 2026). "Early detection is critical to prevent renal function decline and improve outcomes, but conventional biomarkers (e.g., urinary albumin-to-creatinine ratio [UACR] and estimated glomerular filtration rate [eGFR]) have limited sensitivity for early-stage kidney damage." (PMID 42028288, 2026). "In conclusion, AKU-related nephropathy should be evaluated with urine albumin measurement rather than measuring urine protein." (PMID 39836193, 2025). "Moreover, a substantial rise in urinary ALB levels was observed in the PME group (p = 0.0025), suggesting possible kidney damage, as increased albumin excretion in urine can indicate renal dysfunction." (PMID 39861724, 2025). "At the patient’s follow-up 2 months later, urine albumin level was measured as 0.08 mg/m2/h in the 24-h urine sample, showing there was never a development of a nephropathy." (PMID 39836193, 2025). "Nephropathy was mainly assessed via albuminuria, typically using the albumin-to-creatinine ratio (ACR) or albumin excretion rate (AER), typically defined as ACR > 30 mg of albumin per gram of creatinine, or AER ≥ 20 μ g/min, confirmed in at least two samples." (PMID 41346657, 2025). "Albumin, creatinine, and blood urea nitrogen (BUN) are reliable indicators for kidney damage." (PMID 35458182, 2022).
kidney damage (continued). "Microvascular complications (i.e., nephropathy and retinopathy) were estimated by looking at the urine albumin/creatinine ratio (ACR) besides the ophthalmology’s visit notes." (PMID 36039251, 2022). "Urine albumin is important in assessing an individual’s kidney disease, not just to estimate kidney damage, but also for grading according to the 2012 Kidney Disease Improving Global Outcome guidelines." (PMID 35075286, 2022). "Unfortunately neither the classic measurement of urinary albumin excretion nor the novel biomarkers of kidney damage were included in the study protocol as it focused on the NFκB and VEGFR2." (PMID 35643467, 2022). "One T1D subject had an estimated glomerular filtration rate of < 60 ml/min (eGFR 57 ml/min) and one had microalbuminuria (urinary albumin creatinine ratio 8.0 mg/mmol), with all others having no clinically significant nephropathy." (PMID 35418088, 2022). "It is increasingly accepted that albumin excretion is not a good marker of kidney damage in SHR (however, it is still routinely determined), at least not one to indicate an early renal injury, what was repeatedly shown in previous studies, including our own." (PMID 34079459, 2021). "Second, although albuminuria was also a crucial marker for kidney damage, we were unable to perform the analysis on albuminuria, as we did not have urinary albumin data at baseline and during the period thereafter." (PMID 33307922, 2021). "Unfortunately, the records of prolonged follow-up in these patients are not considered or reported and the discussion concerning the albumin dose to be used in order not to induce kidney damage is still open." (PMID 33800425, 2021). "Fifth, the definition of CKD was only based on eGFR which was estimated by the CKD-EPI equation, while other kidney damage markers such as proteinuria level, urinary sediment, and albumin:creatinine ratio (ACR) were not considered." (PMID 33896382, 2021). "After 4 weeks, significant kidney damage was observed in the rats in the Model group; comparatively, JQHF markedly decreased 24 h urinary protein, Total Cholesterol (TC), and increased serum total Albumin (ALB)." (PMID 34526554, 2021). "Proteinuria has been associated with TLR2 activation in the kidneys, leading to inflammation in albumin-overloaded nephropathy rats and patients with non-IgA mesangioproliferative glomerulonephritis." (PMID 32079183, 2020). "Compared to SHR, SHR-Glo1+/− heterozygotes exhibited increased albuminuria (33.62 ± 0.21 vs. 20.09 ± 4.29 mg albumin/g creatinine, p = 0.03), despite comparable histological findings in both strains (data not shown) indicating incipient nephropathy." (PMID 33255888, 2020). "Intake of C. sativus compared with placebo did not significantly affect nephropathy indices including serum urea, serum creatinine, 24-hr urine albumin, and DBP." (PMID 31309071, 2019). "Fourth, the clinical definition of CKD is either decreased kidney function (eGFR < 60 mL/min/1.73 m2) in the absence of persistent albuminuria or having kidney damage (albumin-creatinine ratio > 30 mg/g), which presents for 3 months or more." (PMID 31010424, 2019). "In analyses on diuretics, participants aged 65 and older as well as participants with potential kidney damage (indicated by urinary albumin levels ≥ 20 mg/L) did not have substantially stronger associations of diuretics use and CVM." (PMID 31375970, 2019). "Therefore, we investigated the relationship between markers for the Pi load in serum (serum Pi, BAP, and FGF-23) and urinary albumin excretion expressed as UACR, a clinically reliable marker for kidney damage." (PMID 29311711, 2018). "The analysis focused on comparison of urinary peptides in diabetic patients with nephropathy (n = 121, urinary albumin levels >300 mg/L, DN) vs. patients without evidence of DN (n = 118, urinary albumin levels <30 mg/L, non-DN)." (PMID 29123184, 2017).
kidney damage (continued). "Additionally, we found that spot urine albumin/creatinine ratios (ACR), a known marker of kidney damage, was increased in the intermediate HGI group and, even more, in the high HGI group in comparison with the lowest quartile of HGI." (PMID 29108337, 2017). "Also, blood biochemistry and putative biomarkers revealed kidney damage (CREA and BUN) and liver damage (ALP, AST, and ALB)." (PMID 27983637, 2016). "Raised albumin:creatine ratio as a marker of kidney damage and raised γ -glytamyl transferase as a marker of non-alcoholic fatty liver disease or risky alcohol use, provide a general picture of poor health in women of childbearing age." (PMID 23410045, 2013). "This cross-sectional study was conducted on three groups; 40 diabetic subjects without nephropathy (urinary albumin<30 mg/day), 40 subjects with nephropathy (urinary albumin≥30 mg/day), and 40 healthy subjects as the control group." (PMID 23618325, 2013). "It seems that because UACR assessed the condition of urine albumin excretion based on the ability of kidneys to clear creatinine, the use of UACR marker is preferred to estimate urine albumin level alone for assessing severity of kidney damage." (PMID 24455207, 2013). "SNPs (n = 53) were genotyped using Sequenom in 1467 individuals with T1D (718 cases with proteinuric nephropathy and 749 controls without nephropathy i.e. normal albumin excretion)." (PMID 23555584, 2013). "This association also appeared in early and low-normal ranges of serum albumin: creatinine ratio (s-ACR) (s-ACR < 0.2714 mg/mmol: β = 2.304, p < 0.005 and s-ACR 0.2714–0.3649 mg/mmol: β = 1.000, p < 0.041), suggesting that pl-Hp and ox-LDL rise before overt kidney damage." (PMID 40944271, 2025). "Urine composition was also evaluated, and consistent with the pathological evaluation, angiotensin II infusion caused kidney damage and significantly increased the amount of non-esterified fatty acids (NEFA), total urinary protein, and the albumin-to-creatinine ratio (ACR)." (PMID 33200983, 2020). "However, its predictive ability is limited in that not all diabetic patients with nephropathy exhibit increased levels of urinary albumin." (PMID 31388341, 2019). "The activities and levels of albumin (ALB), alkaline phosphatase (ALP), alanine aminotransferase (ALT), aspartate aminotransferase (AST), urea nitrogen (BUN) and creatinine (CRE) in serum are clinically used as biochemical markers for early liver and kidney damage." (PMID 28883631, 2017). "The study included 50 healthy controls (Group 1), 50 diabetic patients with no nephropathy (Group 2), 50 diabetic patients with nephropathy and a urinary albumin excretion (UAE) of 30–200 mg/24 h (Group 3), and 50 diabetic patients with UAE 200–300 mg/24 h (Group 4)." (PMID 23671859, 2013). "Moreover, we did not measure urinary albumin or the albumin/creatinine ratio (ACR) in order to elucidate mechanisms by which key Narenmandula-modulated DE-miRNAs may oppose nephropathy." (PMID 33299464, 2020). "The observations that albumin secretion is not reduced but ameliorated serum creatinine levels are speculated to reflect the protective effect of febuxostat against progression to late-stage nephropathy." (PMID 30544662, 2018). "In addition NAC may attenuate contrast induced nephropathy, as defined by albumin excretion, and seems to be independent of any effect on creatinine (NAC dosage: 500 mg IV prior to cardiac catheterization)." (PMID 25027749, 2014). "Therefore, even though urinary albumin and UMOD did not associate with many cardiovascular risk factors or kidney damage (as indicated by lower eGFR) in this study, these biomarkers may still be useful to monitor kidney damage." (PMID 37055746, 2023). "BALB/C mice significantly presented increased urinary albumin/creatinine ratio (UACR) with renal lesions in pathology, but C57BL/6 mice were absent from kidney damage." (PMID 29492783, 2018).
kidney damage (continued). "Because nephropathy was not a clear-cut clinical entity, many biomarkers for early detection of Cd induced renal dysfunction such as NAG, albumin, β2-MG, α1-MG etc. had been used in several studies." (PMID 24255836, 2013). "Whereas, serum proteins such as albumin have high molecular weight, it can be concluded that DIZ-induced kidney damage has not been enough to enter proteins into urine, but severely impairs glucose uptake." (PMID 24523762, 2013). "Urine albumin–creatinine ratio (UACR) and eGFR are influenced by non-renal factors and often fail to detect early kidney injury, which limits their specificity for active kidney damage." (PMID 41303131, 2025). "Furthermore, the patients with overt nephropathy had higher HbA1c, total cholesterol, LDL-C, and creatinine levels, and lower albumin concentrations than those without albuminuria." (PMID 32922199, 2020).
renal failure (398 papers, 2005 to 2026). "MTX toxicity is influenced by multiple factors including drug dose, renal insufficiency, advanced age, folate level, serum albumin reduction, and gene polymorphism." (PMID 40626260, 2025). "Similar prognostic abilities of UPCR, UACR, and urine non-albumin to creatinine ratio to predict an associated increased risk for a > 50% decline in eGFR or kidney failure have been demonstrated in additional pediatric CKD studies." (PMID 38509517, 2024). "Other studies examining HPT showed an association between renal insufficiency and serum albumin-corrected calcium or calcium-phosphate product which was not the case in our patient series." (PMID 38027217, 2023). "We tested the known risk factors of a rapid decline of renal function used in the kidney failure risk calculation: age, sex, eGFR, albuminuria, albumin, phosphate, bicarbonate, and calcium at baseline." (PMID 37373661, 2023). "There was a significant correlation between sleep duration and ALB levels in patients with renal insufficiency, and the reason was considered that urinary albumin causes albumin levels to decrease." (PMID 35655296, 2022). "Another study indicated that a lower level of serum albumin predicted a higher risk of kidney failure, which was consistent with our study." (PMID 36046149, 2022). "Serum albumin levels and oliguria/anuria were considered the prominent interactive factors that affect the association between C3 and the risk of kidney failure by the interaction analysis, which remained robust under the grouping of other indicators." (PMID 35874697, 2022). "It has been revealed that a serum albumin level of less than 3.8 g/dL (and/or a reduction in serum albumin levels) confers a greater mortality risk in patients with kidney failure." (PMID 35204237, 2022). "It has been shown that carbamylated serum albumin is a risk factor for in subjects with kidney failure." (PMID 33505488, 2021). "Multivariable logistic regression analyses showed that serum albumin (p = 0.015) and microalbuminuria (p < 0.001) were associated with kidney failure progression in patients with newly diagnosed type 2 DM." (PMID 34268015, 2021). "Serum albumin represents the nutritional status of patients and is reportedly associated with dietary protein intake in peritoneal dialysis patients." (PMID 33912360, 2021). "Renal insufficiency was significantly associated with age, peripheral manifestation, serum albumin, C-reactive protein and erythrocyte sedimentation rate." (PMID 31620002, 2019). "Age ≥60 years and the baseline phosphorus, albumin, and bilirubin levels showed significant associations with renal insufficiency." (PMID 29443737, 2018). "Change in plasma copeptin concentration, 24-hour urine albumin-to-creatinine ratio, measured creatinine clearance, estimated 5-year risk of kidney failure (using the 4-variable Kidney Failure Risk Equation), and health-related quality of life." (PMID 28856009, 2017). "Although initial serum albumin level is highly associated with overall and cardiovascular mortality in peritoneal dialysis (PD) patients, we consider that the dynamic change and trend of albumin after initiation of PD are also essential." (PMID 27015223, 2016). "In 26 229 patients with data for the urine albumin to creatinine ratio, the four variable kidney failure risk equation (KFRE) showed marginal improvement in discrimination over our new equation (C statistic 0.950, 95% CI 0.942 to 0.958 for KFRE v 0.926, 0.915 to 0.936, for the new equation)." (PMID 41658049, 2026). "For example, an AI algorithm could be applied to a validated risk scores such as the Kidney Failure Risk Equation, which estimates the 2- and 5-year risk of kidney failure using age, sex, eGFR, and urinary albumin-creatinine ratio (UACR)." (PMID 40041609, 2025).